HNF1B (HNF1 homeobox B)
Diseases named in the same sentence as HNF1B in open-access papers (continued):
Sharing a sentence is not in itself a finding about the gene and the disease.
Renal cyst (continued). "Predictive factors for detecting HNF1B mutations included bilateral renal anomalies, renal cysts of unknown origin, a combination of two major renal anomalies, and hypomagnesemia." (PMID 39337310, 2024). "Renal cysts are the predominant manifestation among HNF1B-associated kidney diseases, though other renal anomalies, such as a single kidney, renal hypoplasia, and renal dysfunction, including hypomagnesemia or hyperuricemia, may also occur." (PMID 39337310, 2024). "HNF1B directly regulates the transcription of Pkhd1, and inhibition of PKHD1 gene expression may affect the development of renal cysts in humans with HNF1B mutations." (PMID 39337310, 2024). "Mutations in Hnf1β cause renal cysts and renal function decline in both humans and mice." (PMID 36752209, 2023). "This includes not only known Hnf1b-regulated genes, such as Mg2+ transporters, and components of the proximal tubule endocytic uptake machinery but also previously unknown Hnf1b targets associated with cystic kidney disease and renal malformation." (PMID 36522156, 2023). "Nephrologists have also identified autosomal dominant mutation of HNF1B linked with polycystic kidney disease, diabetic nephropathy and cystic kidney disease (CKD) of unknown cause." (PMID 33580750, 2021). "Subsequently, it was shown that in patients with congenital cystic renal dysplasia HNF1B mutations could frequently be identified (renal cysts and diabetes syndrome, RCAD)." (PMID 29497606, 2018). "Mutations in HNF1β can result in a broad range of phenotypes, many of which are common in other cystic kidney diseases and ciliopathies and as such plays a critical role in the diagnostics of cystic kidney disease." (PMID 29479522, 2017). "Moreover, miRNAs that were identified as HNF1B-associated are likely to be involved in regulating metabolic functions associated with renal cyst formation." (PMID 27059371, 2016). "HNF1B mutations and deletions cause renal cyst and diabetes syndrome and hypomagnesemia." (PMID 21858020, 2011). "The prevalence of HNF1B-associated renal disease depends on which study cohort is selected; the detection rate ranges from 5% in children ≤ 16 years with renal aplasia/hypoplasia and chronic kidney disease to 31% in children with renal cysts, hyperechogenicity, hypoplasia or a single kidney." (PMID 30021660, 2018). "Different from other ADTKDs, ADTKD–HNF1B or HNF1B nephropathy presents cystic kidney disease, congenital anomalies of the kidney and urinary tract (CAKUT), and tubular dysfunction." (PMID 39976632, 2025). "Here, we report a novel in-frame deletion of HNF1B in a family with renal cysts and MODY, furthering our understanding of HNF1B-related phenotypes." (PMID 39337310, 2024). "The first described HNF1B-associated renal disorder was Renal Cysts And Diabetes syndrome (RCAD), characterized by renal cysts and Maturity-Onset Diabetes of the Young type 5 (MODY5), with high phenotypic variability." (PMID 39408938, 2024). "The group of syndromic ciliopathies consisted of BBS (n = 3/7, 43%), MKS (n = 2/7, 29%), and HNF1B-related renal cystic disease (n = 2/7, 29%)." (PMID 37635794, 2023). "Oligohydramnios or anhydramnios occurred in fetuses with ARPKD and one fetus with MKS, while there was one case of polyhydramnios in a fetus with HNF1B-related renal cystic disease." (PMID 37635794, 2023). "At median follow-up of 5.4 years (range 3.8-7 years), three of the four remaining HNF1B patients were found to have renal cysts whereas only one of the remaining nine patients with m.3243A>G developed deafness." (PMID 34789499, 2022). "Pathogenic variants of HNF1B are associated with MODY5, renal cysts, abnormalities of kidney and urinary tract, and disorders of Müllerian agenesis." (PMID 36361644, 2022). "In patients with HNF1B-MODY presence of cystic kidneys, pancreatic abnormalities and elevated liver enzymes are common and were used as predictors of HNF1B mutations." (PMID 34299172, 2021).
Renal cyst (continued). "The clinical diagnoses in 16/20 patients (80%) with suspected cystic kidney diseases were confirmed, and one patient was reclassified as carrying a deletion in the hepatocyte nuclear factor-1-beta gene (HNF1B)." (PMID 34295353, 2021). "Of the 20 patients with suspected cystic kidney diseases, the clinical diagnoses for 16 patients (80%) were confirmed, and that of one patient with a deletion in HNF1B was reclassified." (PMID 34295353, 2021). "In this review article we will shortly discuss the most common kidney cystic diseases of infancy – ADPKD and ARPKD – as well as present a clinical case of a rare multisystemic disorder containing kidney cysts – HNF1B-associated disease." (PMID 35474932, 2021). "Cystic kidney disease, including cystic dysplasia, is the predominant form of CAKUT associated with HNF1B mutations." (PMID 32708349, 2020). "The second presented a heterozygous whole gene deletion in HNF1B, DM, renal cysts, body and tail pancreatic agenesis, and hypomagnesemia; this alteration was also found in his two siblings and his father." (PMID 31066763, 2019). "Some of these are included in complex clinical syndromes such as branchio-oto-renal syndrome (EYA1, SIX1), renal-coloboma syndrome (PAX2), renal cysts and diabetes syndrome (TCF2/HNF1B) and Townes–Brocks syndrome (SALL1)." (PMID 28647851, 2018). "Mutation in HNF-1β gene results in MODY type 5 and the patients commonly exhibit notable histological anomalies showing meganephrons, and renal cysts referred as renal cysts and diabetes syndrome (RCAD)." (PMID 29867778, 2018). "The extent and severity of renal disease varies extensively in HNF1β mutations, ranging from congenital anomalies of the kidney and urinary tract (CAKUT), cystic kidneys to hyperuricaemia." (PMID 29764441, 2018). "Especially, regarding HNF1B a rapid increase of participants has been observed ever since HNF1B became a part of the regular genetic screening in patients with hereditary cystic kidney diseases." (PMID 29497606, 2018). "Germline heterozygous mutations in the hepatocyte nuclear factor 1 beta gene (HNF1B, also termed TCF2) cause the renal cysts and diabetes syndrome (RCAD, OMIM #137920)." (PMID 25700310, 2015). "Mutations in the HNF1β gene cause maturity-onset diabetes of the young type 5 (MODY5), renal cysts, genital malformations, and pancreas atrophy." (PMID 26464794, 2015). "The HNF1B gene has been frequently reported in association with maturity onset diabetes of the young type 5 (MODY5), cystic renal disease, renal dilations, pancreatic atrophy, and liver abnormalities also seen in this deletion syndrome." (PMID 24991439, 2014). "Rare mutations in HNF1B have been associated with maturity-onset diabetes of the young subtype 5 (MODY5), renal cysts, pancreatic atrophy, and uterine abnormalities caused by incomplete Mullerian duct fusion and Mullerian duct aplasia." (PMID 22299039, 2012). "There is emerging evidence that rare, predicted damaging variants within cystic kidney disease genes such as PKD2, HNF1B and PKHD1 may have a phenotype modifying role." (PMID 39883360, 2025). "Originally, variations in the hepatocyte nuclear factor-1 β (HNF-1β, OMIM 189907) have been discovered in patients with maturity-onset diabetes of the young, later it has been found to be one major cause of the renal cysts and diabetes syndrome [RCAD; OMIM 137920]." (PMID 36969268, 2023). "Mutations in HNF1B cause a pleotropic set of GU anomalies, including CAKUT and various forms of renal cystic disease (e.g., hyperechogenic kidneys (phenocopying ARPKD), multicystic kidney disease, renal agenesis, renal hypoplasia, cystic dysplasia, and hyperuricemic tubulointerstitial nephropathy." (PMID 37635794, 2023). "Other signals overlapped Mendelian disorder regions, suggesting variable expressivity and broad impact of these loci, as illustrated by signals mapping to Rotor syndrome (SLCO1B1/3), renal cysts and diabetes syndrome (HNF1B), or Charcot-Marie-Tooth (PMP22) loci." (PMID 35240056, 2022).
Renal cyst (continued). "As the HNF1B protein is involved in the transcription of various genes, congenital anomalies of the kidney and urinary tract, such as dysplastic kidney and renal aplasia, as well as renal cysts can be found in the kidney." (PMID 36362756, 2022). "HNF1B has not been described in kidney cancer, but dysfunction in HNF1B is known to cause developmental kidney diseases and renal cysts." (PMID 33842927, 2021). "The expression of HNF1β was also down‐regulated in cystic kidneys." (PMID 33512774, 2021). "Additionally, Hnf1b deletion in medullar tubules at relatively later stages resulted in cystic kidneys after birth and downregulation of several cystic disease genes, including the HNF1B direct targets Pkhd1, Pkd2, Kif12 and Umod." (PMID 33737325, 2021). "In contrast, Weber’s study showed that HNF1B and PAX2 mutations caused CKDs with an age of onset between 10 and 23 years, and autosomal recessive polycystic kidney disease was reported to be the most prevalent etiology in neonatal-onset cystic kidney diseases." (PMID 34295353, 2021). "Mutations in HNF1B in humans lead to maturity-onset diabetes of the young, type 5 (MODY5), cystic kidney disease, multicystic dysplastic kidneys, glomerulocystic kidney disease, autosomal dominant tubulointerstitial kidney disease, and congenital anomalies of the kidney and urinary tract (CAKUT)." (PMID 33809516, 2021). "None of the unsolved patients had have family history of kidney disease, therefore mutations in autosomal recessive genes that lead to ARPKD-like phenotypes such as the DZIP1L or even in dominant cystic kidney disease genes such as HNF1B, PKD1 and PKD2 that often occur de novo are possible." (PMID 32799815, 2020). "HNF1B's effects on the kidneys may include renal cysts, solitary kidney, horseshoe kidney, renal dysplasia, and hydronephrosis (Clissold, Hamilton, Hattersley, Ellard, & Bingham, 2015)." (PMID 31056860, 2019). "Targeted knockdown of Hnf1b in mice results in liver cysts and renal cysts." (PMID 29576871, 2018). "Given the role of HNF1β as a master regulator of a number of cystic kidney disease genes including PKHD1 and PKD2, there is a credible genetic cause which might explain the resemblance between HNF1β and ARPKD/ADPKD patients." (PMID 29479522, 2017). "Given the Wnt11 deficiency dependent changes in the kidney tubular system we also examined possible changes in the genes encoding the “core” PCP pathway and certain other genes (e.g. TCS2, PDK1 and HNF1b) involved in cystic kidney diseases by qRT-PCR using E16.5 and NB kidneys." (PMID 27582005, 2016). "Indeed, renal cysts are frequently observed in HNF1B patients and animal models." (PMID 39408938, 2024). "Nevertheless, these organoids did not develop renal cysts (as happen in Hnf1b–/– mice and individuals with heterozygous mutations in HNF1B) highlighting the key phenotypical and mechanistic differences between organoid models and the in vivo patho-biology of the disease." (PMID 33250772, 2020). "It is noteworthy that not all patients carrying an HNF1B mutation have renal cysts or DM." (PMID 31066763, 2019). "Moreover, mutations in HNF1β can inhibit PKHD1 gene expression and may contribute to the formation of renal cysts in humans with MODY5 (maturity-onset diabetes of the young type 5) and congenital cystic abnormalities of the kidney." (PMID 28398236, 2017). "We report a novel in-frame deletion of HNF1B in a family with renal cysts and MODY, furthering our understanding of HNF1B-related phenotypes." (PMID 39337310, 2024). "The patient in Case 2 (a 13-year-old girl) had a variation in the HNF1B gene (MODY 5) and was also clinically diagnosed with HNF1B MODY due to short stature, abnormal renal function, renal cysts, unicornuate uterus, and diabetic ketoacidosis at presentation." (PMID 39420905, 2024).
Renal cyst (continued). "We describe two unrelated individuals with early onset cystic kidney disease and unaffected parents, where a combination of next-generation sequencing of cystic genes including PKHD1, HNF1B and PKD1 allowed the identification of biallelic PKD1 variants." (PMID 37372410, 2023). "HNF1β-MODY is characterized by renal dysfunction, including renal cysts, renal dysplasia, pancreatic atrophy, and genital abnormalities." (PMID 34746319, 2021). "A cystic kidney disease panel should include adequate coverage of PKD1, PKD2, PKHD1, Daz-interacting zinc-finger protein 1-like (DZIP1L), HNF1B and genes for other ciliopathies such as nephronophthisis (NPHP) and Bardet–Biedl syndrome (BBS)." (PMID 31118499, 2019). "Most patients with HNF1B-related nephropathy typically present with simple renal cysts without a significant decrease in kidney function." (PMID 39337310, 2024). "In addition to regulating mitochondrial OXPHOS/FAO functions, ERRγ also cooperates with HNF1β to activate the expression of renal reabsorption genes including PKD2; deletion of ERRγ in renal tubular epithelial cells results in renal cysts." (PMID 39000280, 2024). "About the clinical features of HNF1B-MODY, known as Renal cysts and diabetes syndrome (RCAD), this subtype is often accompanied by variable phenotypes including malformation of the pancreas, urogenital abnormalities, renal cysts, and neurocognitive defects." (PMID 39191897, 2024). "There are no reported ocular features for the HNF1B gene which is affected in HNF1B-nephropathy, formerly known as renal cysts and diabetes syndrome." (PMID 37468646, 2024). "The disease was originally described as renal cysts and diabetes syndrome (RCAD), as kidney cysts (present in 60% of all patients) and maturity-onset diabetes of the young (MODY5) (40%) are common in patients with HNF1β defects." (PMID 35554666, 2022). "Structural kidney disease (renal cysts, dysplasia and hypoplasia/agenesis that are the cardinal features of HNF1B disease) was not reported in any of the patients diagnosed by unselected genetic testing." (PMID 34789499, 2022). "Knockout of HNF1β decreased the expression of miR-200 and increased the expression of miR-200 targets, including Zeb2 and Pkd1 in HNF1β knockout mouse kidneys, supporting that HNF-1β regulates EMT and cystic kidney disease via repressing the expression of miR-200." (PMID 33809516, 2021). "Indeed, > 50% of these patients presented with a positive genetic test in the absence of a family history of cystic kidney disease, and most of them showed pathogenic variants causative of ADPKD, followed by ARPKD and HNF1B-nephropathy." (PMID 39384646, 2025). "Based on clinical, imaging, and biological variables, MODY5 was suspected due to young-onset DM, normal BMI, renal cysts, insulin secretion dysfunction, negative autoantibodies to IA-2, and an HNF1B score of 14, which is a pivotal tool for rational genetic testing." (PMID 39337310, 2024).
type 2 diabetes (69 papers, 2008 to 2026). "Maturity onset diabetes of the young type 5 linked to HNF1B is an important component and often presents beyond early childhood." (PMID 41465172, 2025). "Diagnosis of type 2 diabetes was assumed until genetic study revealed that she carried the same HNF1B variant than her daughter." (PMID 36793123, 2023). "The first pathogenic variant of HNF1B (namely, R177X) was reported in 1997 and is associated with the maturity-onset diabetes of the young." (PMID 36672242, 2023). "The first HNF1B pathogenic variant (R177X) was described in a Japanese family with maturity-onset diabetes of the young (MODY), in 1997." (PMID 36672242, 2023). "HNF1B mutations cause maturity-onset diabetes in the young type five; therefore, we next considered the influence of HNF1B on metabolism in CCC." (PMID 34067626, 2021). "Similar evidence comes from HNF1B, for which type 2 diabetes risk alleles are associated with ovarian cancer but the direction of effect varies by subtype (serous vs clear cell)." (PMID 32705315, 2020). "One study found that 10 out of 36 type 2 diabetes risk alleles were nominally inversely associated with prostate cancer, with only the HNF1B risk allele remaining significant following multiple testing correction." (PMID 32705315, 2020). "Common variants in the hepatocyte nuclear factor 1 homeobox B (HNF1B) gene are associated with the risk of Type II diabetes and multiple cancers." (PMID 25378557, 2015). "Recently, it is becoming well known that most of OCCCs express HNF1β, a transcription factor, which is closely associated with the development of liver, pancreas and kidney, as well as occurrence of familial forms of type 2 diabetes." (PMID 26375553, 2015). "Mutations in HNF1β (also known as TCF2, previously discussed) have been associated with maturity-onset diabetes of the young renal dysfunction and Müllerian aplasia." (PMID 25506511, 2013). "HNF1B variants were implicated in a slightly reduced risk of type II diabetes mellitus in AAM and EAM." (PMID 24386569, 2013). "For example, variants in TCF7L2 predispose to both colon cancer and type 2 diabetes while variants in HNF1B predisposes to type 2 diabetes and prostate cancer." (PMID 22809218, 2012). "Genome-wide association studies have found type 2 diabetes-associated variants in the HNF1B gene to exhibit reciprocal associations with prostate cancer risk." (PMID 20526366, 2010). "Maturity-onset diabetes of the young subtype 5 is caused by mutations in the HNF1B gene." (PMID 37016461, 2023). "There has been evidence that changes in the HNF1B gene contribute to a slight predisposition to type 2 diabetes, Possibly caused by mutations in the HNFB1 gene that create a protein that is incapable of binding DNA or fails to transactivate DNA following binding." (PMID 37063851, 2023). "Several type 2 diabetes susceptibility genes are known to play a role in cancer development (e.g. TCF7L2, CDKN2A/B, AKT2, PPARG, PTEN and HNF1B) but the evidence is relatively scarce for shared genetic aetiology between type 2 diabetes predisposing alleles and the observationally associated cancers." (PMID 32705315, 2020). "HNF1B is a member of the homeodomain-containing superfamily of transcription factors (TFs), and SNPs at this locus are already known to be associated with risk of Type II diabetes, prostate cancer and two different ovarian cancer subtypes." (PMID 25378557, 2015). "At the same time, a genetic factor may also be responsible for this proliferative effect, since the HNF-1β allele (hepatocyte nuclear factor 1 homeobox B) increases the risk of developing type 2 diabetes and also reduces the likelihood of developing prostate cancer." (PMID 29147337, 2013). "Maturity-onset diabetes of the young type 5 is a signature feature of HNF1B disruption, yet it rarely defines the early paediatric years." (PMID 41465172, 2025).